TNF (tumor necrosis factor)
Diseases named in the same sentence as TNF in open-access papers (continued):
Sharing a sentence is not in itself a finding about the gene and the disease.
Oral ulcer (32 papers, 2006 to 2026). Erosion of the mucous mebrane of the mouth with local excavation of the surface, resulting from the sloughing of inflammatory necrotic tissue. "The serum levels of TNF-α were found to have strong association with oral ulcer (P = .00),genital ulcer (P = .00), the presence of positive pathergy test (P = .00),ocular lesion (P = .00), and vascular lesion (P = .000)." (PMID 19197380, 2008). "Furthermore, in individuals with mouth ulcers, the TNF-α mutation (TC; n=81) was more common than wild-type TNF-α (CC; n=16)." (PMID 41821754, 2026). "In oral ulcers, the application of acetic acid elevated proinflammatory cytokines such as TNF-α, NF-κB, and IL-6 buccal contents by 246%, 345%, and 558%, respectively, compared with the normal control group." (PMID 40809172, 2025). "Chamomile extract can accelerate the healing of traumatic oral ulcers by reducing epithelial cell apoptosis and TNF‐α expression in diabetic rats." (PMID 39949885, 2025). "The topical application of chrysin significantly reduced the levels of IL-6 and TNF-α in acetic acid-induced oral ulcers." (PMID 40809172, 2025). "The bacteria involved in oral ulcers stimulate host oral cells to produce various cytokines such as IL-8 and TNF-α, further aggravating tissue destruction in this disease." (PMID 40696693, 2025). "The levels of inflammatory cytokines IL-6, TNF-α, IL-18, and IL-1β in the oral ulcer group were significantly higher than in the normal group." (PMID 40818135, 2025). "Qu and colleagues similarly utilized Sprague Dawley rats and microneedle patches loaded with TA@MPDA-HA/BSP and reported a significant reduction in inflammation (decrease in TNF-α), accelerated epithelial regeneration, and rapid recovery from oral ulcers." (PMID 40871046, 2025). "Exos regulated immune activity by reducing the levelsof inflammatory cytokines IL-2 and TNF-α in LPS-stimulated macrophages.In the SD rat oral ulcer model, MN patches accelerated wound closure,outperforming other treatment groups." (PMID 41358115, 2025). "Dermatologists should be aware of the risks associated with initiating therapy and maintain a low threshold of suspicion for this infection in patients on anti-TNF-⍺ inhibitors presenting with oral ulcers." (PMID 37720115, 2023). "When TA@MPDA-HA/BSP MNs were used to treat oral ulcers, the area of oral ulcers and inflammatory factor level such as TNF-α and CD31 were significantly reduced." (PMID 37214298, 2023). "The combination ofA. catechu andD. grandiflora extract in the oral gel can optimize the healing of traumatic oral ulcers in Sprague-Dawley rats through the increase of TNF-α and collagen deposition." (PMID 41018047, 2021). "After normalizing saliva for protein content, BD patients with oral ulcers (BD-MA) had significantly higher levels of salivary IL-1β (p=0.01), IL-8 (p=0.02), TNF-α (p=0.004) and IL-6 (p=0.01) than HCs." (PMID 35003055, 2021). "For those with oral ulcers, TNF-α likely plays a beneficial role in recruiting immune cells to battle pathogens associated with the wound." (PMID 35003055, 2021). "In the component-key target network, PTGS2, referred to as cyclooxygenase 2 (COX2), MMP9, and TNF-α are the top three degree-ranked targets, which were considered as the important roles in oral ulcers treatment of KYQG." (PMID 32811507, 2020). "The results of the experimental verification indicated that KYQG significantly inhibited the serum levels of cyclooxygenase-2 (COX2), matrix metalloproteinase 9 (MMP9) and tumor necrosis factor-alpha (TNF-α) in rats with oral ulcer." (PMID 32811507, 2020). "Chamomile extract can optimize the healing of traumatic oral ulcers in diabetic rats through the reduction of apoptosis in the epithelium and TNF-α expression." (PMID 27383710, 2016).
Oral ulcer (continued). "Therefore, chrysin’s ability to reduce NF-κB activation and subsequently lower cytokine levels, such as IL-6 and TNF-α, is a crucial aspect of its therapeutic potential in managing oral ulcers and other inflammatory conditions." (PMID 40809172, 2025). "Similarly, other preclinical models have shown that PTX significantly reduces the expression of TNFα and IL-1β, thereby promoting the healing of radiotherapy-induced oral ulcers." (PMID 41164763, 2025). "Controlling the overexpression of cytokines such as TNF-α may be useful in reducing pain and accelerating the healing of oral ulcers in rats, as it reduces acute inflammation." (PMID 37627569, 2023). "Thus, chamomile extract can optimize the healing of traumatic oral ulcers in diabetic rats through the reduction of apoptosis in the epithelium and TNF-α expression." (PMID 27383710, 2016). "KYQG markedly diminished inflammation and enhanced the healing of oral ulcers, as evidenced by reduced levels of inflammatory markers including COX-2, MMP-9, and TNF-α." (PMID 39907951, 2025). "DEX not only reduces the production of inflammatory cytokines, such as IL-6, TNF-α, and NO, by LPS-induced inflammation but also reduces MDA levels in rabbits suffering from oral ulcers." (PMID 36474235, 2022). "To demonstrate the reliability of our method, we conducted the animal experiment on an oral ulcer model in rats and detected the serum levels of COX2, MMP9, and TNF-α." (PMID 32811507, 2020). "Classifying these additional patients under ICBD facilitated the initiation of approved biologic treatments (e.g., monoclonal anti-TNF), potentially improving the management of BD, particularly in patients with ocular involvement and without oral ulcers." (PMID 40807180, 2025). "In this study, saliva TNF-α was significantly increased in both BD patients with and without oral ulcers." (PMID 35003055, 2021). "Particularly, TNF signaling pathway and HIF-1 signaling pathway may play crucial roles in the protection of KYQG against oral ulcers." (PMID 32811507, 2020). "KYQG exhibited the therapeutic effects on oral ulcers probably by inhibiting inflammation, regulating immunological response, and suppressing oxidative stress based on 47 key targets, such as MMP9, COX2, and TNF-α." (PMID 32811507, 2020). "Notably, BD patients without oral ulcers (BD-MQ) also had significantly higher salivary IL-1β, IL-8 and TNF-α (p ≤ 0.05) than HCs." (PMID 35003055, 2021). "The elevated saliva cytokines IL-8, IL-1β, and TNF-α in BD patients without oral ulcers could be included in a potential cytokine panel to assist in the differential diagnosis, predicting the reoccurrence of ulcers or systemic relapse, and monitoring treatments." (PMID 35003055, 2021). "None of the TNF family members (TNF-α, APRIL, BCMA, and BAFF) we investigated showed any significant difference in expression between patients with or without other active clinical manifestations (oral ulcers, genital ulcers, vascular and cutaneous lesions, and pathergy test)." (PMID 25759827, 2014).
Seizure (32 papers, 2012 to 2025). A seizure is an intermittent abnormality of nervous system physiology characterized by a transient occurrence of signs and/or symptoms due to abnormal excessive or synchronous neuronal activity in the brain. "Although some studies have suggested that epileptic seizures cause an increase in cytokines, we detected reduced cytokine levels, although only the differences in sIL-2R and TNF-α levels were statistically significant (p < 0.05)." (PMID 40124353, 2025). "Research has shown that epileptic seizures are linked to heightened levels of PICs, primarily IL-1β, IL-6, and TNF-α." (PMID 38405667, 2024). "Epileptic seizures are associated with elevated levels of proinflammatory cytokines, including TNF-α, which mediate the impact of neuroinflammation hyperexcitability of the brain and epileptogenesis." (PMID 36142325, 2022). "Seizure‐induced neuroinflammation is a condition associated with the increase of cytokines such as interleukin (IL)‐1β, tumor necrosis factor (TNF), transforming growth factor (TGF)‐β, and danger signals such as High Mobility Group Box 1 (HMGB1)." (PMID 32140642, 2020). "In seizure models induced byPTZ, an increase in the levels of IL-1β, IL-6, and TNF-α cytokines in the hippocampus of rats has been reported." (PMID 40969414, 2025). "Elevated concentrations of pro-inflammatory cytokines, notably interleukin-1β (IL-1β), IL-6, and tumor necrosis factor-α (TNF-α), have been linked to epileptic seizures." (PMID 38390593, 2024). "The expression of fecal TNF-α was markedly higher in seizure group than that in remission group and control group, while it was also markedly higher in remission group than that in control group, and there were statistically significant differences (P<0.05)." (PMID 38699693, 2024). "Seizure incidence and severity in TNFα–/–, TNFR2–/–, and TNFR1–/–TNFR2–/– mice during the acute infection period was therefore evaluated." (PMID 28497109, 2017). "Previous research reported that the TNF-α mRNA peaked at 6 h following limbic seizure with epilepticus." (PMID 24381640, 2013). "Seizure activity rapidly increases the synthesis and release of TNF-α, which acts on endothelial cells and changes the BBB permeability." (PMID 24040253, 2013). "TNF-transgenic mice, especially homozygous mice, showed a lower weight gain and developed spontaneous epileptic seizures." (PMID 22848506, 2012). "The plasma elevation of proinflammatory cytokines (IL-1; IL-6; TNF-alpha; INF-gamma), which is traditionally associated with epileptic seizures, is countered by the elevation of anti-inflammatory mechanisms (IL-10; Fractalkine; GCSF) and the decrease in plasma concentration of IGF-1." (PMID 40076950, 2025). "Seizures induce an inflammatory cytokine storm characterized by activation of glial cells and release of pro-inflammatory factors such as interleukin (IL)-1β, IL-6, and tumor necrosis factor (TNF)-α." (PMID 38332381, 2024). "Seizures can induce alterations in the expression of IL-1β and TNFα." (PMID 29867355, 2018). "In addition, both seizures and SCI were highly associated with TNF levels; therefore, for achieving a better curative effect on SCI, TNF and other major hubs should be targeted together according to the theory of network intervention, rather than a single target such as TNF alone." (PMID 30700814, 2019). "The levels of TNF-α and IL-1β were significantly elevated in the PTZ-induced seizures model compared to the control group, which were reduced after the treatment of CA." (PMID 39901156, 2025). "Next, to further explore whether the inflammation was caused in PTZ-induced seizures model and examine the effects of CA on pro-inflammatory cytokines in PTZ-induced kindling model mice, western blotting was performed to examine the levels of TNF-α and IL-1β in the hippocampus of mice." (PMID 39901156, 2025).
Seizure (continued). "Seizure, neuronal apoptosis, oxidative stress (increased SOD and GSH-Px expression and decreased MDA and 8-OHdG expression) and inflammation (reduced IL-1β, TNF-α, and IL-6 expression) were reduced by miR-485 in epileptic cells." (PMID 34021541, 2021). "In this study, we found that IL-6 and TNF-α serum levels were significantly higher in FS patients than in febrile children without seizures, and IL-6 and TNF-α levels positively correlated with the serum levels of IL-1β in children with FS." (PMID 38218765, 2024). "In addition, the excessive release of pro-inflammatory mediators, such as interleukins, tumor necrosis factor-alpha (TNF-α), and nuclear factor kappa B (NF-κB), was found to enhance neuronal hyperexcitability and epileptic seizures." (PMID 37509594, 2023). "In a study comparing serum levels of TNF-α and interleukin 4 (IL-4) in patients with febrile seizures versus controls (febrile patients without seizure or history of febrile seizures), it was found that both TNF-α and IL-4 concentrations were significantly higher in patients with febrile seizures." (PMID 31394791, 2019). "Therefore, we infer that the anticonvulsive effect of UR, RP, and VA—at least for proinflammatory cytokines IL-1β, IL-6, and TNF-α—did not play a key role in the KA-induced acute seizure." (PMID 24381640, 2013). "Thus, in the current report we examined the effects of inhibiting microRNA‐155 (miR‐155) on the levels of IL‐1β, IL‐6 and TNF‐α, and expression of GAT‐1 and GAT‐3 in the parietal cortex, hippocampus and amygdala of rats with nonconvulsive seizure (NCS) following cerebral ischaemia." (PMID 31144434, 2019).
Atrophy (31 papers, 2011 to 2026). Any weakening or degeneration, especially through lack of use. "The results showed that the expression of the inflammatory factor TNF-α in the group treated with enalapril significantly decreased compared to the atrophy group (**P < 0.01)." (PMID 38887391, 2024). "The results showed that the expression of the inflammatory factor TNF- α in the group treated with WBM significantly increased compared to the atrophy group (p<0.01)." (PMID 39086863, 2024). "For example, in atrophy models induced by TNF-α, hydrogen peroxide, dexamethasone, and angiotensin II, researchers suggested that miR-29b participates in the pathogenesis of atrophy." (PMID 39126043, 2024). "The results showed that TNF-α levels in the group treated with WBM (182±0.25 pg/g) decreased compared to the atrophy group (223±0.82 pg/g) in the recovery phase (p<0.05)." (PMID 39086863, 2024). "1,25VD3 downregulated the increased expression of muscle atrophy-associated proteins, including FoxO3a, MAFbx, and MuRF1 in an IFN-γ/TNF-α induced atrophy model." (PMID 38004107, 2023). "The results showed that, after 7-days of immobilization, the total expression of inflammatory biomarkers of muscle tissues (IL-6, TNF-α) was significantly reduced in the H2-treatment group compared to the atrophy group (p < 0.05)." (PMID 37895907, 2023). "Two ubiquitin ligases, MAFbx and MuRF1, have previously been shown to be rapidly induced in multiple models of muscle atrophy, including the TNF-α-induced muscle wasting model." (PMID 34724970, 2021). "One theory is that eosinophils are mediated by specific types of T-helper cells that result in higher cytokine production, including TNF-α and IL-9, and this contributes to interstitial atrophy, irreversible fibrosis, and eventually ESKD." (PMID 31931743, 2020). "Patients with higher scores in the variable tubular atrophy/interstitial fibrosis grade showed higher serum levels of TNF-α [T2:10.60 (8.25–12.85) pg/mL vs. T1: 9.20 (8.00–10.20) pg/mL vs. T0: 8.20 (6.70–10.05) pg/mL, overall P = 0.001]." (PMID 30428849, 2018). "It is well established that the serum levels of proinflammatory cytokines, particularly IL-1β and TNF-α, are elevated in cachectic patients contributing to muscle atrophy." (PMID 26064425, 2015). "This is the first study to show an increase in the expression of TNF-α during disuse-induced atrophy in humans." (PMID 21845220, 2011). "Thus, TNF-α-induced muscle atrophy models are widely used to study muscle degeneration and evaluate therapeutic interventions." (PMID 40136713, 2025). "Furthermore, in a TNF-α-induced atrophy model, both treatments of heat-killed HY7715 and HY7715-derived EVs restored the mRNA level MYOG to near-control levels, indicating their protective effect against inflammatory muscle damage." (PMID 40724603, 2025). "Furthermore, systemic inflammation and elevated serum TNF-α levels were implicated in various pathologies involving muscle atrophy, and GDF-15 was reported to be induced by inflammatory cytokines such as TNF-α." (PMID 38515869, 2024). "Some scholars believe that NF-κB activation-induced muscle atrophy may be related to the increase of inflammatory factors such as TNF-α and IL-6, and blocking this pathway may represent a promising target to treat muscle atrophy." (PMID 38509497, 2024). "Furthermore, the mRNA expression level of TNF‐α was significantly decreased in the BRE group than in the atrophy group (**p < .01)." (PMID 39619947, 2024). "RSV has also been shown to upregulate the phosphorylation of protein kinase B (Akt), p70 ribosomal S6 protein kinase (p70S6K), mammalian target of rapamycin (mTOR), and eukaryotic translation initiation factor 4E- (eIF4E-) binding protein 1 (4E-BP1) in TNF-α-induced atrophy." (PMID 38020198, 2023).
Atrophy (continued). "MRI type 2 had more severe deep WMH, lacunes in the white matter, no microbleeds or atrophy, and less severe clinical manifestations and was associated with upregulation of TNF-α compared with MRI type 1." (PMID 32485815, 2020). "Moreover, ILCs express TLR3 and are functionally able to respond to poly I:C with increased synthesis of TNF-α thus contributing to small intestinal atrophy." (PMID 25950701, 2015). "The absence of a correlation between Aβ and TNF‐α, and hippocampal atrophy in MDD may be linked to undisclosed factors related to non‐amyloid‐mediated processes." (PMID 39236111, 2024). "Cardiac atrophy and dysfunction results from an abnormally altered metabolism (e.g., MHC shift, insulin deficiency), leading to an imbalance in protein synthesis and degradation, increased systemic inflammation via upregulation of IL‐6 and TNFα, as well as altered energy availability." (PMID 37654192, 2023). "Compared with TNF‐α treatment, DHM inhibited the expression of atrogin‐1 and MuRF1, two atrophy‐related genes." (PMID 34676967, 2021). "In addition to CAPN3, we evaluated the levels of TNF-α and NF-κB to assess the responses of catabolic metabolism to the treatments used in the STZ-induced atrophy model." (PMID 38020198, 2023). "Skeletal muscle tissue levels of IL-6 and TNF-α in the atrophy group were higher than control, and treatment with HRW significantly prevented the rise in tissue levels of these inflammatory markers compared to the atrophy group." (PMID 37895907, 2023). "No previous study has shown evidence that TNF-α is involved in disuse atrophy in humans; instead, it has been shown to activate NF-κB in several diseased states resulting in muscle atrophy." (PMID 21845220, 2011). "IL-6 and TNF-α levels were elevated in both plasma and thymus tissues at 24 h post-CLP, which could imply a potential role of inflammatory processes in acute thymic atrophy." (PMID 40715082, 2025).